IL6 (interleukin 6)
Diseases named in the same sentence as IL6 in open-access papers (continued):
Sharing a sentence is not in itself a finding about the gene and the disease.
cancer (continued). "Therefore, the present study investigated whether blocking IL-6/IL-6R/STAT-3 signaling disrupts proliferation, migration, invasion and clonogenicity of PCa cells; these processes are essential to metastasis in cancer." (PMID 35703345, 2022). "This could be a likely scenario in the IL-6-rich BM microenvironment of MDS patients, since MDSCs are known to escape necroptosis after DNA methylation following IL-6-induced STAT3 signaling in the context of cancer." (PMID 36013147, 2022). "The GSVA analysis of cancer hallmarks revealed that the high expression of BARX1 might trigger unfolded protein response, MYC target, and oxidative phosphorylation, and suppress apoptosis, IL6–JAK–STAT3 signaling, and inflammatory response." (PMID 36353226, 2022). "IL-6 has been shown to promote survival of transformed cholangiocytes through a number of pathways, including the p38 and p44/42 MAPK pathway and through DNA methylation of the promoter region of target genes involved in cancer growth, such as the epidermal growth factor receptor (EGFR)." (PMID 35565248, 2022). "However, many inflammatory cytokines, such as IL-1, IL-6, IL-12, TNF-α, secreted by M1 macrophages are also important mediators of EMT, which could improve cancer-cell motility and invasiveness." (PMID 35794526, 2022). "Interestingly, IL-6 together with leptin can increase the expression of procollagen-lysin-2-oxoglutarate 5 dioxygenase (PLOD2), a protein involved in ECM remodeling, and therefore has a decisive role in cancer cell invasion and EMT." (PMID 35625629, 2022). "Miyake and coworkers were evaluated the anti-inflammatory effects of HMB in TE-1 cancer cells and reported that HMB administration could downregulate IL-6 production by regulation of inhibitor of kappa B alpha (IĸBα) phosphorylation and reduction of nuclear translocation of NF-ĸB/Rela." (PMID 35148750, 2022). "In cancer cells, a general activation of signaling pathways such as mitogen-activated protein kinase (MAPK), phosphoinositide 3-kinase (PI3K), STAT3, and nuclear factor κB (NF-kB) pathways happens, whereupon they promote the expression of IL-6, IL-10, GM-CSF and TGF-β, among others." (PMID 35267487, 2022). "However, IL-6 appears to promote metastasis primarily as an inflammatory factor capable of mediating epithelial-to-mesenchymal transition (EMT), a key phenotype of metastatic cancer cells." (PMID 35053592, 2022). "In addition, select immune mediators and cancer biomarkers also exhibited high importance scores in our analyses for predictions of LD and vaginal pH (MIF), as well as genital inflammation (IL-6, IL-10, MIP-1α), further confirming the link between vaginal microbiota and host immune responses." (PMID 35196323, 2022). "The anti-cancer activity was assessed in histological preparations of breast organs, CD4+/CD8+ T cells from spleen organs, and several essential cytokines involved in breast cancer, such as IL-1, IL-6, TNF-α, IFN-γ, TGF-β, and IL-10, in the blood serum of mice." (PMID 35765486, 2022). "Therefore, IL-6 works synergistically with the TFs NF-kB and STAT3, as well as multiple miRNAs, to set up dynamic regulatory feedback loops for perpetuating inflammatory cues that promote chronic inflammation and cancer." (PMID 35757000, 2022). "Interleukin-6 (IL-6) is a critical mediator of HCC development and is involved in the regulation of cancer stem cell proliferation, differentiation, invasion, metastasis, and angiogenesis through a number of signaling pathways, such as STAT3 signaling, which drives cancer progression and metastasis." (PMID 35432524, 2022). "Therefore, it is possible that in our population of dogs with carcinoma, collection of blood at a single time point did not allow for complete evaluation of the influence of IL‐6." (PMID 34881459, 2022).
cancer (continued). "While earlier reports suggest that IL-6 can independently induce EMT-like features in multiple cancer types, in our study, at the stipulated dose, simultaneous addition of IL-6 with TGF-β did not enhance a robust EMT feature, as evident from the expression of EMT-associated markers." (PMID 35127527, 2021). "ANXA1 also promotes the proliferation and metastasis of cancer cells through the binding of EphA2, the suppression of autophagy and the activation of the PI3K/AKT pathway and promotes proliferation and migration via the regulation of the IL-6/JAK2/STAT3 pathway." (PMID 34439260, 2021). "First, consistent with the role of inflammation in cancer development and progression, we observed a significant upregulation of Th1 pro-inflammatory cytokines in both solid and haematological malignancy patients compared to HCWs, including TNF-α, IL-6, and IL-1Ra." (PMID 34830872, 2021). "Accordingly, we identified that the levels of IL-6 and TGF-β were significantly increased in the medium of Mφ cells cocultured with MCF7-TAMR1 cells, which again could be functionally related to the expression of SGLT1 in the cancer cells." (PMID 34006822, 2021). "Therefore, as a scientific approach to cancer cachexia, many attempts have been made to inhibit cancer cachexia by targeting the inflammatory cytokines, tumor necrosis factor alpha (TNF-α) and interleukin (IL)-6." (PMID 34262449, 2021). "However, leptin may expand cancer cells through the production of cytokines by macrophages and also upregulate the pro-inflammatory cytokines such as TNF-α and IL-6 and stimulated the macrophage function." (PMID 34360753, 2021). "Thus, the therapeutic benefit we see in vivo appears to be independent of IL-6 activity directly on the cancer cells and most likely mediated by its impact on the stroma." (PMID 34711820, 2021). "As such, we demonstrate that both canonical and non-canonical STING signaling can participate in the rapid IL-6 production seen upon DNA damage in different cancer cells, indicating that the pro-tumorigenic activities of the pathway are not limited to its chronic engagement." (PMID 35087822, 2021). "Interestingly, the cytokines IL-6, IL-8 and TNF-α that were detected in the supernatants of the SeNps-treated cells, have been previously reported to be released by cancer cells undergoing ICD and to be involved in the signalling of dendritic and natural killer cells." (PMID 34771499, 2021). "Researches showed editing role in the pathogenesis of cancer and indicated its relation with mediators such as tumour necrosis factor-α (TNF-α), soluble TNF-related apoptosis-inducing ligand (sTRAIL), interleukin-6 (IL-6), pentraxin-3 (PTX-3), procalcitonin (PCT), and Creactive protein (CRP) levels." (PMID 33776564, 2021). "We found IL-6 more frequently positive among malignant tumors than non-malignant samples." (PMID 34284788, 2021). "As a common effector of TLR4 and inflammatory cytokine receptors that promote muscle wasting including TNFα, IL-6, IL-1β and members of the TGFβ superfamily including TGFβ and activin A/myostatin, p38β MAPK plays a central role in mediating muscle wasting in murine models of cancer." (PMID 34950660, 2021). "However, in human non-cancer colon fibroblast cells, GAE promoted anti-inflammatory activities, which was accompanied by the reduction of intracellular ROS and the inhibited expression of TNF-α, IL-1β, IL-6, and NF-κB." (PMID 33664749, 2021). "Therefore, exploring biomarkers related to the IL6-JAK-STAT3 pathway may be potentially valuable for the detection and treatment of cancer." (PMID 34869039, 2021). "The classical and alternative IL-6 signaling pathways activate JAKs with subsequent activation of the signal transducer and activator of transcription-3 (STAT3), a key transcription factor inducing numerous effector genes involved in cancer promotion and malignancy." (PMID 34445170, 2021).
cancer (continued). "On the one hand, monotherapy with anti-inflammatory agents has been proved limited efficacy in cancer treatment, for example, monotherapy with agents targeting IL-6 only showed moderate activity against solid tumors in non-stratified patients (NCT00841191, NCT01531998)." (PMID 34248142, 2021). "Thus, induction of pro‐inflammatory signalling (including IL‐6 secretion) via upregulation of HSP70 in omTU and/or omTAM might be involved in promoting the peritoneal spread of cancer cells in HGSC patients." (PMID 34841720, 2021). "Dysregulation of miR-133a-3p may also have an accumulative harming effect that may lead to either one or both of cancer and non-cancerous conditions (target genes IL6, and FGF2)." (PMID 34440025, 2021). "This concurrent induction of Il-6, Rsad2 and Ifit1 by CPT in TC-1 cells prompted us to broadly assess whether such convergent induction of the NF-κB and IRF3 branches was a frequent response to DNA damage in cancer cells." (PMID 35087822, 2021). "Furthermore, calcitriol inhibited IL-6 expression and EMT changes in irradiated cancer cells." (PMID 34109109, 2021). "Interleukin IL-6 a pro-inflammatory cytokine overexpressed in the epithelium of prostatic intraepithelial lesions (PIN), may regulate androgen receptor activity promoting cancer development and progression." (PMID 35111194, 2021). "While warranting further studies in larger datasets of cancer cells, this constitutes, to our knowledge, the first direct evidence that cell-intrinsic canonical STING signaling frequently contributes to the production of pro-tumorigenic IL-6 upon DNA damage in cancer cells." (PMID 35087822, 2021). "This might be due to the effects of IL‐6 and TGF‐β1 in the cancer sites." (PMID 34570961, 2021). "Therefore, there is a possibility that SASP-related factors including IL-6 from the cells showing senescence-related features, promote the proliferation of non-irradiated cancer cells." (PMID 34948029, 2021). "Besides cancer cell lines, δ-tocotrienol inhibits the expression of pro-inflammatory markers such as IL-6 and NFκB in human umbilical vein endothelial cells (HUVECs) and TNF-α, IL-6, and iNOS in macrophages." (PMID 34072997, 2021). "Furthermore, increased expression of KRAB-ZNFs is significantly associated with the downregulation of many proinflammatory signaling pathways in KIRC, especially those mediated by interferons, IL2, IL6, or TNF-α, which was previously shown to enhance cancer stemness maintenance." (PMID 34638319, 2021). "Furthermore, IL-6 has a major role in the communication between the cancer cells and the non-malignant cells within the tumor niche." (PMID 34200156, 2021). "However, IL‐6 and TGF‐β1 were upregulated in cancer nodules." (PMID 34570961, 2021). "Thus, the presence or absence of IL-6 dictates doxorubicin efficacy by shifting its mechanism of anti-cancer clearance, which becomes primarily immunogenic in the absence of IL-6." (PMID 34711820, 2021). "In this study, activated CAFs induced by IL-6 could express α-SMA, acquire a highly contractile phenotype, and functionally, activated CAFs could facilitate GC cell proliferation, which resulted in co-evolution of CAFs with cancer cells." (PMID 33824303, 2021). "Mirroring macrophages, the IL-6 enriched in the GC-MSC-CM can stimulate the phosphorylation of STAT3 and ERK1/2 in neutrophils, promoting their recruitment and activation into a pro-tumor phenotype that would finely cooperate with GC-MSC to synergistically prompt cancer migration and angiogenesis." (PMID 34046337, 2021). "Recent, some inhibitors of IL-6/STAT3 have been development, such as S31-201 or IL-6 neutralizing monoclonal antibody (IL-6 mAb), Madindoline A (Inhibits the dimerization of IL-6/IL-6R/gpl30 trimeric complexes), C188-9 and Curcumin (Inhibits STAT3 phosphorylation), etc. for treatment of cancers." (PMID 34976809, 2021).
cancer (continued). "It was found to be related to the modulation of the interleukin 6 (IL-6)/JAK/signal transducers and activators of transcription 3 (STAT3) signaling pathway, which is involved in the proliferation, progression, and metastasis of cancer cells (Johnson, O’Keefe & Grandis, 2018)." (PMID 34178453, 2021). "βAR signaling stimulates the expression of TGFβ, VEGF, IL-6, MMP9, and PTGS2 by macrophages, thereby promoting tumor progression and inhibiting the transcription of type I and II interferons, which are important in cell-mediated immune responses against cancer." (PMID 34207620, 2021). "It is well known that angiogenesis plays an essential role in the progression of cancer; IMiDs also have an anti-angiogenetic effect, reducing tumor necrosis factor-α (TNF-α), vascular endothelial growth factor (VEGF), fibroblast growth factor-β (FGF-β) and interleukin-6 (IL-6)." (PMID 32899586, 2020). "Hence, this provides further evidence for IL6 and STAT3 being viable targets for cancer therapy." (PMID 31936675, 2020). "* Via physical contacts with cancer cells and through secreted factors, theyincreased CSC proportions, as well as EMT and migration.* The activities of the myeloid cells were mediated by or connected to solublefactors such as TNFα, IL-6 and ELR+ CXC chemokines (e.g., CXCL8 and CXCL1)." (PMID 33585241, 2020). "Moreover, IL-6 activates STAT3 and NF-κB by (i) autocrine and paracrine signaling and (ii) via synergistic crosstalk between the pathways in BC cells, resulting in cancer cell proliferation and apoptosis evasion." (PMID 31963198, 2020). "Cancer cell EMT could be driven by paracrine signals from the microenvironment, such as TGF-β, Wnt, Notch-1, Sonic Hedgehog (Shh), and pro-inflammatory cytokines including tumor necrosis factor alpha (TNF-α) and IL-6." (PMID 32242230, 2020). "However, we can speculate that IL‐6, IL‐11, and LIF secreted by PC may be responsible for some of them, as they have well‐known roles in cancer." (PMID 32767843, 2020). "Moreover, this metabolic responses seem to be mediated by secretion of pro-inflammatory cytokines from cancer cells and also from the immune system of the host, including tumor necrosis factor (TNF), interferon-gamma (IFN-γ), and several interleukins (IL-6, IL-1β)." (PMID 32230855, 2020). "In previous studies of gastric cancer, IL-6 has been shown to induce the M2 differentiation and increase the expression of TGF-β and IL-10 in TAMs via promoting STAT3 phosphorylation and activation, and this phenomenon augments the proliferation and migration of cancer cells." (PMID 33114183, 2020). "The results suggest that a protein panel of the inflammatory biomarkers YKL-40, IL-6, and CRP, and the cancer biomarkers CEA and CA19-9 might identify patients that benefit from more aggressive treatment and surveillance, although the additional value of IL-6 and CRP in this aspect is limited." (PMID 32756596, 2020). "Interleukin-6 (IL-6) has been proven to be a significant nonmatrix target of MMPs in cancer growth and development by modulating many signaling molecules, in particular signal transducer and activator of transcription-3 (STAT-3) and extracellular signal-regulated kinase (ERK) 1/2." (PMID 33014057, 2020). "In TME, IL-6 could be produced by inflammatory cells 9, cancer cells 10, and MSCs 10-12, while hyperactivation of IL-6/JAK/STAT3 signaling pathways within a TME contributes to aggressiveness and progression of cancer through multifaced mechanisms." (PMID 32127934, 2020). "Nevertheless, unlike healthy controls and cancer patients not suffering weight loss, IL-6 plasma levels were strongly elevated, which fits the observation that ZAG expression is stimulated by hormones such as IL-8, leptin and IL-6." (PMID 32315567, 2020).
cancer (continued). "Tamoxifen inhibits cancer cell interactions with platelets, which decreases platelet activation and the release of TGF-β1, platelet derived growth factor (PDGF), vascular endothelial growth factor (VEGF), interleukin 6 (IL-6) and insulin like growth factor (IGF-1) from platelets into the TME." (PMID 32532126, 2020). "Thus, LPS-triggered expression of IL-6 and AAT may actually help cancer cells to escape apoptosis and/or to increase proliferation." (PMID 32533048, 2020). "However, while IL‐6 is pro‐tumorigenic supporting cellular proliferation, metastases and survival through mechanisms including activation of the JAK/STAT3 signaling pathways, high levels have been reported to be a poor prognostic marker in cancer." (PMID 32383556, 2020). "However, IL-6 alone was not superior to the predictive value of other conventional biomarkers and tests in distinguishing benign and malignant ovarian masses." (PMID 32042020, 2020). "Although this phenomenon has largely been seen among cancers that have surrounding inflammation as a source of IL-6, we have previously reported absence of MSH3 expression within the epithelium of hamartomatous polyps, which contain inflammation but are not neoplastic." (PMID 31789935, 2019). "Moreover, immunohistochemical staining of human GC tissues in the present study showed that IL-6 expression was localized to the stromal cells and not the cancer cells." (PMID 30927911, 2019). "Hence, an inflammatory signal from non-transformed, spontaneous, immortalized cells to cancer cells initiates a positive feedback loop involving IL-6/NF-κB/Lin28/let-7 miRNA and STAT3 activation." (PMID 31557902, 2019). "As for other cytokines, IL-6 driven-effects are also extended to other pathways, thus regulating several biological responses in target cells, including the activation of MAPK, PI3K, and Notch, which play an important role in inflammatory disease and cancer development." (PMID 30927908, 2019). "In cancer cachexia, lipolysis is activated by various factors, including enhanced stimulation of β-adrenergic receptors; increased secretion of cytokines, such as TNF-α, IL-1, IL-6, and interferon-γ; and increased expression of lipid-mobilizing factors, such as zinc-α2 glycoprotein-1 (AZGP1)." (PMID 30754663, 2019). "Similarly, one study showed that both SRH and vital exhaustion were positively correlated with the level of pro-inflammatory markers such as IL-6 and hs-CRP, which could lead to inflammation resulting in cancer or cardiovascular diseases." (PMID 31800615, 2019). "Interestingly, GSI treatment decreased both IL-6 and IL-8 expression but not TGFB1 that has been associated with the development of a secretory phenotype of cancer cells." (PMID 31597699, 2019). "Furthermore, CpG-MCA nanohydrogels effectively induced high expression of tumor necrosis factor-α and interleukin-6, and remarkably inhibited the proliferation of U251 cells, suggesting that CpG-MCA nanohydrogels are expected to be employed as the potent anti-cancer immunostimulant." (PMID 31243604, 2019). "Proinflammatory cytokines IL‐6 and IL‐8 showed negative correlation with ER status, while IL‐6 correlated positively with Ki67 status, which indicated increased inflammation in ‘ER Low & Ki67 High’ cancers." (PMID 30451357, 2019). "Although some types of cancer cells can release certain cytokines, cachectic cancer cells do not necessarily release catabolic cytokines such as TNFα, IL-6, and IL-1β, and the vast majority of circulating cytokines are generated by immune cells in response to cancer." (PMID 31480237, 2019). "There are several reasons to explain why the level of IL-6 in plasma significantly increased on POD 1, including surgical stress or physical trauma that induced the production of IL-6 from normal human cells—as IL-6 is an essential factor for wound healing —and from the cancer microenvironment." (PMID 31010015, 2019).